EGFR (epidermal growth factor receptor)
Diseases named in the same sentence as EGFR in open-access papers (continued):
Sharing a sentence is not in itself a finding about the gene and the disease.
tumor (continued). "As measured by histological analysis, ABY-029 performed expectedly better in the visualization of EGFR-expressing tumors (91% accuracy, 80% overall accuracy), while 5-ALA performed better in the visualization of the tumor margins of non-EGFR-expressing tumors (87% accuracy, 84% overall accuracy)." (PMID 32582530, 2020). "However, when any invasive tumor cell staining was counted, the positivity rates increased to 52.3% for EGFR and 58% for CK5/6." (PMID 32364614, 2020). "Beyond the well-established role of Src kinases family in tumor initiation, progression and invasion, c-Src activation plays a key role also in the acquisition and maintenance of resistance to EGFR inhibitors in human lung, breast, colorectal and pancreatic cancer." (PMID 32517369, 2020). "Therefore, we determined the possible mechanism of these three effective EGFR-TKIs in lymphangiogenesis and tumour metastasis in NSCLC models in vitro and in vivo." (PMID 31892990, 2020). "Epidermal growth factor receptor (EGFR) overexpression has been found in up to 70% of BCa tumours." (PMID 33396795, 2020). "Intrinsic resistance to these TKI drugs tends to be uncommon in EGFR‐positive tumours." (PMID 34766125, 2020). "Analysis limited to patients in whom the tumor PD-L1 expression was evaluated in tissue specimens obtained before the start of the first-line EGFR-TKI treatment showed similar results (7/10 patients (70.0%) vs. 3/12 patients (25.0%); p = 0.084, Fisher’s exact test)." (PMID 33255696, 2020). "Another factor could be related to the utilization of primary tumor tissue to establish the patient’s EGFR status, but it is the metastases stage, which is biologically distinct from the primary tumors, that is treated with cetuximab." (PMID 33324546, 2020). "As this pathway is central for the tumor behavior, often associated with oncogene addiction, for diagnostics and therapy design, in this work, all NSCLC analyses were performed under consideration of the EGFR/KRAS mutational background." (PMID 32605217, 2020). "Taken together, the response of tumor cells to TRAIL might also be related to the expression level of EGFR." (PMID 32413049, 2020). "It is already known that EGFR-TKIs delay tumor progression greater than chemotherapy." (PMID 33194721, 2020). "For example, the proportion of the tumour with only EGFR amplified, AE, is calculated as(3.1)AE(t)=∫0LH(E(x,t)−0.1K)H(0.1K−P(x,t))dx∫0LH(E(x,t)+P(x,t)+N(x,t)−0.1K)dx,(3.2)≈Number of mesh points with E>0.1K and P<0.1KNumber of mesh points with T>0.1K,where H(·) is the Heaviside step function." (PMID 33120534, 2020). "Even if the EGFR mutation is negative, due to the small number of remaining tumour cells available for analysis, samples often cannot be tested for ALK." (PMID 33425389, 2020). "Tumor cells may transfer EGFR into the cytoplasm by endocytosis to avoid excessive signaling by the feedback system." (PMID 32833992, 2020). "Of the 29 EGFR-mutated NSCLC tumor specimens, high (2+ to 3+) and low (no to 1+) AXL expression was observed in 6 (21%), and 23 (79%) specimens, respectively." (PMID 32929081, 2020). "Pb-S01 and Pb-M01 both demonstrated EGFR staining in H292 xenograft tumor sections." (PMID 32246002, 2020). "Especially in a subgroup with tumour content ratio below 10%, one-third of the EGFR mutation false negative samples with the cobas method at first turned to be positive at the re-test after the dissection." (PMID 32028905, 2020). "ERBB2 amplification has been identified as a resistance mechanism induced upon treatment with erlotinib or gefitinib and was observed in 12% of tumor samples obtained from patients at resistance to EGFR TKI therapy; however, its role in afatinib resistance is unclear." (PMID 32477948, 2020).
tumor (continued). "Additionally, both T790M mutation and EGFR-KDD amplification were reported in biopsies of EGFR-KDD tumour specimens post EGFRi treatment, suggesting shared resistance mechanisms with classical EGFR mutations to targeted therapy." (PMID 31562956, 2020). "In addition, a strong positive correlation between normalized total EGFR and tumor uptake of the radiotracers was achieved (r = 0.8469, p = 0.025)." (PMID 32295603, 2020). "Here, we revealed that 24% of the cobas negative samples showed positive EGFR mutations after performing tumour dissection on a slide with bronchoscopic biopsied samples." (PMID 32028905, 2020). "It is well known that the presence of KRAS and BRAF mutations in a patient’s tumor correlates strongly with resistance to anti-EGFR antibodies, and therefore, all patients are tested for BRAF and KRAS mutations before initiating anti-EGFR therapy." (PMID 32290033, 2020). "Whereas there is evidence to the effect that tumor sidedness may predict response to anti-EGFR monoclonal antibodies, the evidence specifically for Bevacizumab is not very robust." (PMID 32612957, 2020). "This disadvantage (false positivity) of EGFR testing using FFPE tumor also suggests that if liquid biopsy sensitivity can rival that of tumor biopsy, it may become a good surrogate for tissue EGFR testing, since it usually shows low false positivity." (PMID 33266057, 2020). "It seems that the key point of the anti-tumor mechanism is abundant EGFR internalization causing by noncompetitive antibody combination." (PMID 32336949, 2020). "In two different human tumor cell lines, these EGFR-targeting miRNA polyplexes conferred selective, enhanced delivery of miRNA-200c, leading to various anti-tumor effects, including decreased tumor cell proliferation and migration, and enhanced sensitivity towards doxorubicin." (PMID 32917034, 2020). "EGFR mutation assays are mainly performed on tumor biopsies, which carry risks, are not always successful and give results relevant to the timepoint of the assay." (PMID 33117705, 2020). "Additionally, the two distinct EGFR‐CAR NK cells inhibited the growth of the TNBC tumor both in vitro and in vivo." (PMID 32592435, 2020). "Activation of CD73 on tumor cells favors cell adhesion through epidermal growth factor receptor (EGFR) and releases matrix metalloproteinases (MMPs) that facilitate the breakdown of extracellular matrix (ECM), thus enabling tumor cells to migrate to distant organs." (PMID 32411209, 2020). "Furthermore, NB-PDT has proven very effective in inducing tumor necrosis in an orthotopic mouse model of head and neck cancer expressing EGFR, and to induce significant tumor regression in an orthotopic mouse model of breast cancer expressing HER2." (PMID 32326519, 2020). "In solid tumors the main target of these drugs are oncoproteins crucial for tumor maintenance and survival such as epidermal growth factor (EGFR), B-Raf proto-oncogene/serine/threonine kinase (BRAF), proto-oncogene c-Kit (KIT), human epidermal growth factor receptor 2 (HER2)." (PMID 32218226, 2020). "In addition, osimertinib as adjuvant therapy for stage IB–IIIA EGFR-mutant NSCLC after complete tumor resection also achieved meaningful survival results." (PMID 33109256, 2020). "In two patients with non-small cell lung cancer (NSCLC), EGFR T790M mutations were identified in the plasma, while tumor biopsies tested negative for this genetic aberration." (PMID 32748806, 2020). "However, when plasma cfDNA analysis is used as a predictive and follow-up tool in EGFR-mutated NSCLC, we believe this is less relevant as mutations can be matched to tumor tissue." (PMID 33138052, 2020).
tumor (continued). "Thirdly, previous studies indicated that EGFR mutations were associated with low response rates to PD-1 blockade treatment among patients with NSCLC; in some cases, inhibition of checkpoint blockade even increased the rate of tumor growth considerably." (PMID 32043180, 2020). "After a period of time, tumor cells were able to restore drug sensitivity again, suggesting that clonal evolution persisted, and ctDNA can be used to dynamically monitor KRAS mutation levels, providing a basis for reapplication of anti-EGFR drugs." (PMID 32258135, 2020). "The somatic alteration EGFR exon 2–28 duplication existed in both preimmunotherapy and postimmunotherapy tumor tissues, which suggested that it might be associated with HPD." (PMID 32581041, 2020). "Moreover, pharmacological experiments also indicated that LINC00152 and EGFR have synergistic effects on anti-tumor treatment in vitro and in vivo." (PMID 32774169, 2020). "EGFR is a prime target for cancer therapy across various tumor types." (PMID 33142709, 2020). "Additionally, anti-EGFR-nanobody micelles carrying doxorubicin and anti-EGFR-nanobody liposomes carrying kinase inhibitors demonstrated enhanced anti-tumor efficacy in vivo." (PMID 32793488, 2020). "It is suggested that HGF may promote the immune escape of tumor cells through overexpression of PD‐L1 in EGFR‐TKI‐resistant NSCLC cells; HGF also induces PD‐L1 expression in NSCLC cells by activating PI3K/AKT, MAPK, and AP‐1." (PMID 32875727, 2020). "Tumor genetic analysis is not only useful for monitoring the disease but also for determining the response to treatment, as is the case with anti-EGFR therapy in which only patients with the non-mutated KRAS gene respond." (PMID 32629823, 2020). "Moreover, FGF-2 leaking out from gefitinib-treated NSLC cells was proposed as a survival factor for tumor cells that remained alive after the first exposure of EGFR-TKIs and further maintained their resistance to EGFR-TKIs." (PMID 32599808, 2020). "Moreover, by ablating individual enhancer activity by CRISPR interference, these enhancers are rewired in ecDNA to enhance oncogene EGFR expression and tumor fitness, suggesting a novel mechanism of enhancers in regulating oncogene amplification." (PMID 33046109, 2020). "Moreover, activation of the EGFR pathway increases the production of tumor-derived vascular endothelial growth factor (VEGF), which acts on endothelial cells in a paracrine manner to promote angiogenesis." (PMID 33537237, 2020). "Similarly, the negative filter was strong activated, and the positive filter was nearly shut down with EGFR-wild-type tumor fed to the deep learning model, which reveals the strong classification ability of the deep learning model." (PMID 33067442, 2020). "A protein (Lingzhi-8, LZ-8) from Ganoderma Lucidum was reported that it had anti-tumor activity and could modulate EGFR expression but its binding site on EGFR and mechanism are still unclear." (PMID 32079107, 2020). "Plasma genotyping is widely used as a screening test for detection of the EGFR T790M resistance mutation, with tumor biopsy needed only if the result is negative." (PMID 32010431, 2020). "Dramatic tumor response to EGFR blockade was observed only in a small proportion of patients." (PMID 32292420, 2020). "In general, squamous patients with NSCLC bear a heavier tumor mutational burden with exception of targetable genomic mutations (e.g., EGFR, KRAS, or ROS1) than nonsquamous patients with NSCLC." (PMID 31693178, 2020). "However, it did specifically penetrate into the brain metastatic lesions (EGFR+) caused by hematogeneous metastases, which is absolutely required for this antibody to inhibit the extravascular VEGF produced by tumor cells." (PMID 31768815, 2020).
tumor (continued). "As EGFR‐rich EVs are mainly derived from tumour cells for effective metastasis, our finding should also have broad implications for the tumour biology field and may advance the detection and treatment of multiple human tumour metastases." (PMID 33304472, 2020). "Studies showed that these two antibodies could inhibit EGFR downstream pathway signalling, thus blocking the proliferation, migration and invasion of tumor cells by competing binding to EGFR with EGF." (PMID 33023595, 2020). "Thus, future work is needed to dissect EGFR-mediated tumor-TAM feedbacks, and more broadly, which other mechanisms are most important." (PMID 32665556, 2020). "A growing body of evidence suggests that metastases may be driven through EV-mediated activation of the EGF receptor-ligand pathway, accomplished through tumour derived EV dissemination of EGFR, AREG or EGF to local and distant cells." (PMID 33143170, 2020). "ESMO CRC Guidelines advocate Early tumor shrinkage (at 8 weeks) as a reasonable exception which could warrant usage of anti-EGFR agents in right sided first line mCRC treatment." (PMID 32612957, 2020). "Furthermore, to understand the effect of LV-miRzip-21 following silencing of critical upstream targets, we transfected HCT116 and GBM8 tumor cells with siRNA for EGFR and AKT prior to LV-miRzip-21 treatment." (PMID 32019988, 2020). "With this method, we found that EGFR mutation types did not concomitantly coexist in all tumor cells." (PMID 32093629, 2020). "All 15 TNBC PDXs were responsive to Pan-HER treatment, showing significant reductions in tumor growth consistent with Pan-HER-mediated tumor downmodulation of EGFR and HER3 protein levels and significantly decreased activation of associated HER family signaling pathways AKT and ERK." (PMID 32414394, 2020). "In addition, in vivo experiments were performed to study the regulatory role of exosomal miR-148a-3p in the ERRFI1/EGFR/MAPK axis affecting tumor formation and angiogenesis in nude mice." (PMID 33117083, 2020). "The combinatorial treatment strongly inhibited the phosphorylation of ERK, thus confirming that this combined treatment acts by inhibiting cell proliferation in line with previous reports indicating that inhibition of EGFR and ICs counteracts tumor cell growth." (PMID 32024070, 2020). "Because the activation of EGFR and TGFα autocrine loop occurs in changing cysts of multiple target organs, this pathway might be exploited as a potential target for anti-tumor therapy for VHL patients." (PMID 32432044, 2020). "The EGFR and Mutation venation includes NSCLC, KRAS, Tumor, Target Therapy, NGS, DNA, and MicroRNA." (PMID 32014844, 2020). "Currently, the EGFR monoclonal antibody cetuximab is the only target drug that has been approved by the US FDA in the treatment for HNSCC.CDKN2A, a tumor-suppressor gene which encodes the cell cycle regulator p16INK4a, has been extensively investigated to be associated with HNSCC." (PMID 33456497, 2020). "It has been documented that the constitutively activation of EGFR or its transactivation could contribute to drug resistance in different types of tumor cells." (PMID 32911509, 2020). "We hypothesized that the effect of bevacizumab-mediated tumor hypoxia could be counteracted by EGFR inhibition, partially explaining the detrimental effects when combining both antibodies in clinical trials." (PMID 33092032, 2020). "This study highlights the importance of promoting ubiquitination-dependent Mcl-1 turnover might be an alternative strategy to enhance the anti-tumor efficacy of EGFR-TKI." (PMID 32276600, 2020). "There are different theories about the coexistence of EGFR mutations and ALK rearrangement in NSCLC—the two gene alterations coexist in different areas (i.e., different cells) of the tumor or are present in the same tumor cells." (PMID 33363040, 2020).
tumor (continued). "The observations of less than 5% VAF of the IDH1 mutation in cases 3, 5, and 6 in a contexts of 51%‐70%, 31%‐50%, and 41%‐60% estimated tumor cellularity and 33%, 13%, and 18% VAF of the coexisting EGFR, KRAS, or PIK3CA mutation suggest presence of IDH1 mutation in a tumor subpopulation." (PMID 32333643, 2020). "When any positivity in invasive tumor cells was included, 69 cases (52.3%) were positive for EGFR." (PMID 32364614, 2020). "Moreover, when gold nanorods were conjugated with monoclonal antibodies against epidermal growth factor receptor (EGFR), the inhibitory effects on tumor growth were enhanced, increasing the antitumor effects of AuNP-induced photothermal therapy." (PMID 32806755, 2020). "Interestingly, to increase the delivery in tumor cells, these nanoparticles are modified with the addition of an anti-EGFR antibody." (PMID 33271894, 2020). "This study clearly demonstrated that the anti-EGFR sdAbs could inhibit cancer cell growth in vitro and tumor growth in vivo." (PMID 33023595, 2020). "Although this is limited to one patient, results are in-line with a recent study suggesting that EGFR-mutated NSCLC patients with KRAS mutations detected in tumor before the start of treatment do not benefit from EGFR TKIs." (PMID 33520716, 2020). "According to GSEA based on MDM2 expression, the ERBB2 and tumor angiogenesis pathways activated by MDM2 amplification may serve as important pathways inducing primary resistance to EGFR-TKIs." (PMID 32611363, 2020). "It is thus tempting to hypothesize that EGFR-mediated complement activation may, in certain situations, may promote tumour growth." (PMID 32054454, 2020). "In our study, EGFRover was enriched in bone metastases, suggesting that organ-specific factors such as its stiffness or tumour microenvironment might result in regulation of harbouring and/or nesting of EGFR-positive tumour cells." (PMID 32901137, 2020). "Genomic analyses have demonstrated multiple abnormalities such as activating kinase mutations in EGFR and PDGFRA in malignant glioma, but the success of targeted therapy has been limited to date, which may be at least in part due to tumor heterogeneity." (PMID 32133357, 2020). "The S100A9 and EGFR suppressions decreased tumor cells viability and Cisplatin-resistance." (PMID 32795296, 2020). "One explanation might be tumor-related alteration of the expression of EGFR and EGFR ligands, which is reflected in the blood." (PMID 32317675, 2020). "Indeed, prior studies have established enhanced anti-tumour efficacy of the EGFR inhibitor (or antibody) with radiation or cytotoxic drugs for A431 cells." (PMID 32093123, 2020). "Serum EGFR, which is known as a tumor marker for several cancers, is detected in healthy individuals or cancer patients as a soluble isoform that only contains the extracellular domain of the full-length EGFR." (PMID 33005239, 2020). "Treatment with AB095-PBD (non-tumor targeted antibody-drug conjugate) alone, and in combination with navitoclax, caused a reduction in tumor volume within both PDX models tested; however, ABBV-321 responses were significantly greater, supporting EGFR-mediated effects." (PMID 33256808, 2020). "EGFR status in NSCLC may vary according to the tumor staging or histological subtypes, and heterogeneity could exist between primary and metastatic site, making results from above researches inconclusive." (PMID 32742498, 2020). "Detection of EGFR mutations is a challenge in many patients due to the lack of suitable tumour specimens for molecular testing or for other reasons." (PMID 32664868, 2020). "The mutation results in the tumor tissue were used as the standard reference for calculating sensitivity, specificity, positive and negative predictive values of EGFR plasma test." (PMID 32746896, 2020).